CXCL13 (C-X-C motif chemokine ligand 13)
Diseases named in the same sentence as CXCL13 in open-access papers (continued):
Sharing a sentence is not in itself a finding about the gene and the disease.
tumor (continued). "Taken together, CXCL13 and CXCR5 usually act as oncogenic cascades in the promotion of tumor cell survival, proliferation, migration, and invasion, and represent therapeutic targets for the development of novel anti-cancer drugs." (PMID 34947813, 2021). "As a chemokine, CXCL13 binds to its homologous receptor CXCR5, participates in the migration and recruitment of lymphocytes, which helps to enhance the immune response of tumor host." (PMID 34736480, 2021). "After data processing, we also found that the expression of CXCL1, CXCL10, CXCL11, CXCL13, and CXCL14 was significantly increased in tumor tissues, and the difference between CXCL10 was the most significant." (PMID 34794429, 2021). "The CXCL13/CXCR5 axis plays pivotal roles in the dissemination and accumulation of malignant lymphocytic cells and in shaping such a tumor-stromal cell microenvironment interaction network." (PMID 34947813, 2021). "Compared with that in healthy donors, the ability of cTfh cells to express effector factors CXCL13 and IL-21 in patients with PDAC was significantly impaired and was further impaired in higher tumor stages." (PMID 34359579, 2021). "Although CXCL13 mediates the recruitment of immune cells to the TLS in the intra- and extra-tumor regions, the specific functions and molecular mechanisms of these cells still need to be further investigated." (PMID 34947813, 2021). "In turn, CXCL13 overexpression seems to attract effector/cytotoxic PD-1+ CD4+ T cells to tumor cells, which promotes CD4+ T cell-mediated tumor cell inhibition and killing." (PMID 34795254, 2021). "Endothelial cells from different sources were mixed and assigned to four cell types, including immune EDCs (CCL5 and CXCL13), lymphatic EDCs (PDPN and PROX1), tumor EDCs (ACKR1 and POSTN), and vascular EDCs (PLVAP and SLC9A3R2)." (PMID 34697289, 2021). "Due to the complexities of the CXCL13/CXCR5 axis in tumor milieu, CXCR5 expression status on tumor cells should be carefully assessed in clinical practice." (PMID 35693216, 2021). "B cells homing into the TME via the CXCL13/CXCR5 axis include pro-tumor B cells and anti-tumor B cells." (PMID 34947813, 2021). "Combined single-cell RNA and T cell receptor sequencing showed that tumour-infiltrating CD40LG+ and CXCL13+ T helper cell clusters in a patient with pseudoprogression were dominated by a single IDH1(R132H)-reactive T cell receptor." (PMID 33762734, 2021). "So far, CXCL13 and its related receptor CXCR5 have been proved to regulate cancer cell migration as well as tumour metastasis." (PMID 34427969, 2021). "Our results revealed the important role of Tfh cells in mediating anti-tumor cellular immunity and humoral immunity in PDAC via secreting CXCL13 and IL-21 and determined a novel mechanism of immunosuppression in PDAC." (PMID 34359579, 2021). "The numbers of tumor‐infiltrating CD20+ immune cells (ICs) (p < 0.001), IGKC+ICs (p = 0.023), and CXCL13+ ICs (p = 0.044) were significantly higher in the high HER2‐AAb group than in the low HER2‐AAb group." (PMID 33506656, 2021). "Mounting evidence demonstrates a high concentration of CXCL13 and/or high expression of CXCR5 in tumor tissues or tumor cell lines." (PMID 34947813, 2021). "A difference was found between male mice with and without primary tumor differed in IL-10 and IL-16 levels, which were higher in those with tumor, and in CXCL5, CXCL11, CXCL13, CXCL16, and CCL24 levels, which were higher in those without tumor." (PMID 32545680, 2020). "CXCL13, and its receptor, CXCR5 (CXCL13/CXCR5 axis), serve as an important pathway of tumor proliferation and metastasis 47-49." (PMID 32669964, 2020). "Recent studies have shown that TLS promotes recruitment of lymphocytes to the tumor microenvironment by expressing chemokines such as CXCL10, CXCL12, CXCL13, CCL19, and CCL21." (PMID 31662750, 2019).
tumor (continued). "CXCL13, the corresponding ligand for CXCR5, has been detected in tumor cells, dendritic cells, and T follicular helper cells as well as stromal cells in B cell follicles." (PMID 31663864, 2019). "The tumor cells are commonly positive for CD21, CD23, CD35, CXCL-13 and podoplanin (D2-40), the markers of normal follicular dendritic cells." (PMID 28438212, 2017). "These cells are also likely the main source of CXCL13 that accumulates in the CSF, and intra-tumoral production of this mediator is believed to support the local recruitment of CXCR5+ tumor-infiltrating lymphocytes." (PMID 28603659, 2016). "Thus, our findings suggested the increased serum levels of CXCL13 representing inflammatory activity might be associated with unfavorable characteristics of ENKTL such as tumor burden like previous studies reporting the contribution of CXCL13 to solid tumor progression, that is." (PMID 25966773, 2015). "In contrast, in patients with high tumor burden such as stage III/IV or detectable EBV, the serum CXCL13 was unable to predict prognosis." (PMID 25966773, 2015). "The expression of genes in tumours was low for CD3Z, CD8, CXCL13, SNAI2 and ESR1 (40-DCq <32) and moderate for IGHM, CD4, CXCL9 and FOXP3 (40-DCq 32–35)." (PMID 25970543, 2015). "In the poorly differentiated group, both CXCL13 and CXCR5 were remarkably higher in tumor tissues, indicating that CXCL13 was regionally increased in poorly differentiated HCC tumor tissues." (PMID 26517519, 2015). "The heavily-infiltrated tumor Tfh cells expressed more activation markers, including CD200, CXCL13, ICOS and PDC1, compared to Tfh cells isolated for tumors with low levels of immune infiltrate." (PMID 24762633, 2014). "In several of these cancers, tumor cells were shown to express functional CXCR5 and to migrate towards CXCL13." (PMID 21490903, 2010). "Spatial analysis showed increased density of suppressive immune cells around tumor cells, increased exhaustion phenotype of both CD4 and CD8 T cells expressing chemokine CXCL13, and spatial microcomplex of endothelial and lymphocyte interactions within tertiary lymphoid structures." (PMID 39803458, 2025). "A negative correlation between the density of tumor-infiltrated CD4+CXCL13+ cells pre-NAIC and %RVT (spearman’s r = − 0.6412, p = 0.0002) was observed, and this correlation was more pronounced in post-NAIC (spearman’s r = − 0.7691, p < 0.0001)." (PMID 40295492, 2025). "However, in ccRCC, CXCL13-CXCR5 interactions paradoxically promote tumor proliferation and migration 100, aligning with our observation that reducing IRF4 lowers pro-tumorigenic CXCL13." (PMID 40607252, 2025). "Additionally, APOD+ myCAFs showed significant interactions with cytotoxic T and NK cells through the CXCL13 and CXCL16 signaling pathways, potentially contributing to tumor regression." (PMID 40107247, 2025). "An analysis of all CD8+ cells revealed that CXCL13 + CD8+ cells accumulated inner- and peri-region of the tumour, indicating that they may directly interact with cancer cells." (PMID 40670667, 2025). "Notably, tumor‐reactive gene signatures were enriched in CXCL13+ Tex cells, whereas non‐tumor‐reactive pathways were preferentially enriched in CXCL13− Tex cells." (PMID 40492496, 2025). "By comparing the proportional differences between recurrent and non-recurrent tumor cells, we found that CXCL13+ CD4+ and CD8+ T cell subsets were enriched in non-recurrent tumors." (PMID 40464813, 2025). "In order to infer fate trajectories of these different phenotypes that were clonally linked by a common TCR barcode, pseudotime analysis by Monocle was carried out specifically on cells with tumor-blood-matched TCRs from GZMB+, GZMK+, CXCL13+, Tregs, Prolif, and MAIT populations." (PMID 40299576, 2025). "Interestingly, CD8+ Interferon-stimulated genes (ISGs+) T cells, known for their potent anti-tumor properties, emerged as primary interactors with CD4+ CXCL13+ Tfh, CD8+ CXCL13+ T, and CD8+ Temra cells in the ICB-Rs." (PMID 40054456, 2025).
tumor (continued). "Notably, HER2-CXCR5-CCR6-CAR T cells demonstrated significantly enhanced tumor infiltration compared to conventional HER2-CAR T cells, attributable to their triple-targeting capacity for tumor sites co-expressing HER2, CXCL13, and CCL20." (PMID 40764989, 2025). "Furthermore, we investigated their anti‐tumor potential in vivo, and studies using B16‐CD19 tumor‐bearing mice confirmed that CXCL13‐overexpression significantly enhanced CAR T cell‐mediated antitumor activity, with a prolonged survival period." (PMID 40492496, 2025). "Nano-capture technology of CXCL13 could reduce tBreg differentiation and normalize epithelial-mesenchymal transition in the TME, thereby inhibiting tumor growth and prolonging the PFS in pancreatic cancer, BRAF mutant melanoma, and TNBC murine models." (PMID 39744696, 2025). "Moreover, we observed a positive correlation between malignant S100A14 expression and the relative percentage of CD8+ cytotoxic T cells within the tumor, particularly CD8+ CXCL13+ cells." (PMID 40806532, 2025). "The role of CXCL13 as a potential importance in CRC therapy has been confirmed by other investigators, who also revealed that CXCL13/CXCR5 axis may target tumors by recruiting B lymphocytes, and is essential in the anti-tumor immune response of TME in CRC." (PMID 40943634, 2025). "Combined treatment with anti–PD-1 and anti-ICOSL Abs did not alter local CXCL13 levels in the lungs of tumor-bearing aged mice." (PMID 40198121, 2025). "The high clonal expansion of CXCL13+ CD4+ T cells likely accounts for their increased proportion following D + T treatment compared to D alone, suggesting a role in enhancing anti-tumor effects." (PMID 41045934, 2025). "It suggests that CD4_CXCL13 might interact with CD8+ T cells and B cells in the TME to modulate local tumor immunity in BM." (PMID 40883281, 2025). "In the context of lymph node metastasis, CXCL13-expressing exhausted CD8+ T-cells drive aggressive tumor phenotypes by enhancing interactions with tumor cells and activating ERK signaling pathways in tumor cells." (PMID 40236693, 2025). "Our results revealed distinct patterns that vary between tumor types but globally resemble those of the Tex markers, and in some cases, they are expressed even higher than some Tex cell markers, like LAG3, PD1, TIGIT, and CXCL13." (PMID 40076932, 2025). "Notably, CXCL13 and PD-1 were also detected in some of the IFNβ-expressing CD4+ T-cell clusters in both tumor types." (PMID 38383773, 2024). "Indeed, PD-1high CD4+ T cells isolated from MMRd ECs co-expressed other activation markers such as CD38, HLA-DR, ICOS, BCL6, CXCL13 and KI67, were proven to be tumor-reactive T cells and correlated with improved prognosis in ECs with high TMB." (PMID 39544936, 2024). "Additionally, the CXCL13 gene expresses inhibitory receptors such as PDCD1, CTLA4, LAG3, and HAVCR2, which assist in tumor microenvironment suppression, allowing for OSCC persistence." (PMID 39766858, 2024). "Likewise, CXCL13 and CXCL1 foster tumor development via the AKT signaling pathway, additional chemokines such as CXCL14, CXCL3, and CXCL12 serve as predictive factors." (PMID 38844562, 2024). "Studies have shown that IL-17A can promote ESCC tumor cells to produce more chemokines CCL2, CCL20, and CXCL13, enhance B cell migration, or enhance IgG-mediated antibody and complement-mediated cytotoxicity of B cells to tumor cells to inhibit tumor development." (PMID 39906741, 2024). "Reciprocally, HPV+ tumor cells could directly interact with CD4+T cells and activate CD4_C3_CXCL13 T cell differentiation, which also had elevated secretion of IFNγ." (PMID 39105803, 2024). "Therefore, we proposed that the occurrence of the elevated CD74 isoform ratio that signifies the enrichment of CD8+CXCL13+ Tex cells and C1QC+ TAMs generally exists in the tumor and lymph node of ESCC patients." (PMID 39312471, 2024). "Furthermore, we observed that lower-expression groups of CXCL13 had better DFS and PFS in this tumor." (PMID 39064019, 2024).
tumor (continued). "Although the prevalence of CD8_C8_CXCL13 cells within NPC tumours is relatively low (scRNA-seq cohort: 0-9.89%; Multiplex IHC cohort: 0.5-11%), their proportion was notably higher in early stage NPC tumours compared to those at advanced stages." (PMID 39231979, 2024). "Moreover, qRT-PCR results revealed significant upregulation of CD27, CXCL13, IFNG and GZMB in tumor-specific T cells using." (PMID 39033098, 2024). "The frequencies of the tumor-reactive CD8+_CXCL13 and CD8+_KI67 populations were significantly positively correlated with the frequency of the IFN-producing CD4+_MKI67 population, supporting the concept of a tumor antigen-driven “help” scenario in the TME." (PMID 38383773, 2024). "Furthermore, a distinct subgroup of tumor-infiltrating lymphocytes (TILs), PD1+CXCL13+CD8+T cells was found to localize with TLS and exhibited enhanced anti-tumor effects." (PMID 39493749, 2024). "Similarly, in ovarian tumors, TNF-α is produced in large amounts, promoting a proinflammatory tumor microenvironment and activating NF-κB signaling, which induces the expression of chemokines including CCL8, CXCL13, and CXCL20 to accelerate tumor development." (PMID 38443657, 2024). "Importantly, serum CXCL13 protein levels exhibited significant differences between early and advanced OSCC, with values increasing with tumor progression." (PMID 39344390, 2024). "Tfh could promote TLS formation in tumors through the production of functional cytokines CXCL13/IL-21/LIGHT, activate B cell responses, and inhibit tumor growth." (PMID 38583352, 2024). "We found a negative correlation (r = −0.25, p = 0.046) between OS and CXCL13+ cell density in the tumor compartment (T)." (PMID 38398098, 2024). "Despite the antitumor role of CXCL13 in promoting TLS formation locally, CXCL13 was more frequently expressed in organs affected by side effects but not in tumor tissues in aged mice than in young mice." (PMID 38469550, 2024). "In both the LN and tumor, colocalization of the CD74, C1QC, and CXCL13 mRNAs was observed." (PMID 39312471, 2024). "These CTLs express the CXCL13 gene, a chemoattractant found to induce a population of double-negative B-cells found to be present in multiple tumor lesions." (PMID 39766858, 2024). "CXCL13 promotes the formation of TLS that provide antitumor support through interactions between B cells and T follicular helper (Tfh) cells, and via priming and expansion of effector T cells within the tumor." (PMID 38786066, 2024). "Concurrent intratumoral injection of CXCL13 and CCL21 increased the influx of CC-chemokine receptor 5 (CCR5)-expressing B and CCR5/CCR7-expressingT cells in the TME, inducing TLS formation and resulting in reduced tumor progression in PDAC mice." (PMID 38690273, 2024). "Moreover, anti-tumor chemokine genes including CXCL9, CXCL10, CXCL11 and CXCL13 expressed higher in the high-necroptosis cohort." (PMID 39247606, 2024). "Noteworthily, we identify unique cell populations, including CXCL13+ CAFs and CXCL13+CD8+ T cells, among other immune cells commonly reported in multiple cancers, suggesting the feasibility of using NPC as a model to study the heterogenous TLS in tumours." (PMID 39231979, 2024). "Furthermore, we identified a tumor-specific PD-1+CXCL13+CD8+T cell subgroup within TLS and elucidated its anti-tumor functions." (PMID 39493749, 2024). "In an orthotopic murine model of pancreatic ductal adenocarcinoma, intratumoral injection of the lymphoid chemokine CXCL13/CCL21 induced TLS formation and improved tumor response to systemic chemotherapy with gemcitabine, which was associated with TLS-associated B cell-mediated DC maturation." (PMID 38583352, 2024). "Additionally, HPV+ tumor cells expressing high MHC-II and CXCL13+CD4+ T cell prevalence are indicative of favorable overall survival rates in OPSCC patients." (PMID 39105803, 2024).
tumor (continued). "We characterised surface markers, cytokine production and transcription factor expression in CXCL13-producing T cells in NSCLC tumours and paired non-cancerous lung samples using flow cytometry." (PMID 37520560, 2023). "In contrast, CXCL13+CD8+ T cells showed positive Ti, suggesting that CXCL13+CD8+ T cells may function as effectors for anti-tumour immunity." (PMID 37735150, 2023). "This theory fits well with gain of CXCL13-producing capacity being restricted to tumour-infiltrating T cells and absent in circulating tumour reactive T cells." (PMID 37520560, 2023). "Furthermore, the specific high expression of CXCL13 and CXCR5 in PD1+CD4+ T cells was observed in tumour tissues as well as adjacent tissues." (PMID 36855810, 2023). "On the contrary, CXCL13+ T cells were hardly detected in the tumor microenvironment of non-responsive patients, but a large number of macrophages with immunosuppressive function were enriched." (PMID 37240834, 2023). "Subcutaneous implantation of a CXCL13-producing fibroblastic reticular cell line, of lymph node origin, induced functional TLS formation, increased immune cell recruitment and enhanced anti-tumour immunity." (PMID 37520560, 2023). "While the production of IL-21 and CXCL13 by Tfh cells can stimulate adaptive anti-tumour immunity at a distance, the direct engagement of Tfh cells with B cells through ICOS/ICOSL and CD40L/CD40 binding is also critical to the anti-tumour immune response." (PMID 37936700, 2023). "Because CXCL13 (secreted protein) and CD39 (expressed at higher levels on vessels than on T cells) were not suitable for IF, we used the coexpression of CD103 and PD1 on CD45+CD3+CD8+ T cells as a readout for potential tumor specificity." (PMID 37217652, 2023). "Peripheral CXCR5-negative Tfh-like cells and Tfh that have migrated into the tumor are potent CXCL13 producers, attracting more B cells and CXCR5+ T cells to the TME." (PMID 36836910, 2023). "In addition, we found significant upregulation of the CXCL13, XCL2, and CXCL17 genes in samples with TLS infiltration in the tumor." (PMID 36776859, 2023). "Furthermore, we found that CD4+ CTLs expressed C-X-C motif chemokine ligand 13 (CXCL13), a B cell chemoattractant, and physically interacted with activated B cells in tumor lesions." (PMID 38077321, 2023). "Interestingly, CXCL13 expression facilitates recruitment of B cells, and leads to an immune-suppressive TME, promoting initiation of tumorigenesis, tumour progression and metastasis." (PMID 36248850, 2022). "Elucidating CXCL13/CXCR5 signaling effects and downstream signaling pathways will help investigate the molecular mechanisms that control tumor progression and responses to targeted therapies, accelerating the translation of drug research into clinical precision medicine." (PMID 35702353, 2022). "The transcriptional levels of 5 chemokines (CXCR5, CXCL12, CXCL13, CCL19, and CCL21) that have been reported to be involved in the formation of TLSs were also prominently elevated in both the tumor specimens from mIgG2c-G400R mice and hIgG1-G396R homozygous CRC patients." (PMID 35133976, 2022). "IHC staining indicated that CXCL13 was not expressed in tumor cells but was detected intensively in TLSs and CD4+ TFH cells." (PMID 35053457, 2022). "Finally, we performed qPCR validation in clinical tissue samples and showed highly expressed POSTN, VISG4 in tumor samples, and highly expressed CXCL10, CXCL13, and MMP12 in normal samples." (PMID 36212488, 2022). "C57BL/6 mice, B cell knockout (KO) C57BL/6 mice, anti-CD19, and anti-CXCL13 antibody-treated C57BL/6 mice were used to determine treatment efficacy and generation of tumor-specific CD8+ T cells in response to PD-L1 blockade alone or combination with TLR-7/8 activation." (PMID 35720386, 2022).